SRCIN1 (SRC kinase signaling inhibitor 1)
Description:
Acts as a negative regulator of SRC by activating CSK which inhibits SRC activity and downstream signaling, leading to impaired cell spreading and migration. Regulates dendritic spine morphology. Involved in calcium-dependent exocytosis. May play a role in neurotransmitter release or synapse maintenance.
Synonyms: SNIP; KIAA1684; P140; p140Cap
Tractability: PROTAC: ubiquitination databases record sites on it; its protein half-life has been measured.
Gene: Protein-coding gene on chromosome 17 (38,530,031 to 38,605,952, reverse strand). Ensembl gene ENSG00000277363.
Subcellular location: Cytoplasm; Cytoplasm, cytoskeleton; Cell projection, axon; Cell projection, dendrite; Presynapse; Postsynapse; Postsynaptic density
Subcellular location (Human Protein Atlas): Cell Junctions
Gene Ontology:
Molecular function: protein binding; protein kinase binding
Biological process: negative regulation of protein tyrosine kinase activity; positive regulation of protein tyrosine kinase activity; postsynaptic actin cytoskeleton organization; regulation of cell migration; regulation of dendritic spine morphogenesis; substrate adhesion-dependent cell spreading
Cellular component: actin cytoskeleton; cytoplasm; focal adhesion; glutamatergic synapse; axon; dendrite; postsynapse; postsynaptic density; presynapse; synapse; cytoskeleton
Genetic constraint (gnomAD): Loss-of-function variants: 47 observed, 85.11 expected, observed/expected ratio (o/e) 0.55, 90% interval 0.44 to 0.7. The synonymous counts are far from expectation, so gnomAD's model fits this gene poorly and the ratio says little. Missense variants: 1,417 observed, 1,383.4 expected, observed/expected ratio (o/e) 1.02, 90% interval 0.98 to 1.07. Synonymous variants: 725 observed, 602.45 expected, observed/expected ratio (o/e) 1.2, 90% interval 1.13 to 1.28.
Homologues: Orthologues: macaque SRCIN1 (99% identical), pig SRCIN1 (96% identical), rat Srcin1 (96% identical), chimpanzee SRCIN1 (95% identical), dog SRCIN1 (94% identical), guinea pig SRCIN1 (91% identical), mouse Srcin1 (91% identical), rabbit SRCIN1 (91% identical), tropical clawed frog srcin1 (71% identical), zebrafish srcin1a (60% identical), Drosophila melanogaster CG32809 (23% identical), Caenorhabditis elegans gldi-9 (16% identical), and 1 more. Paralogues in human: KIAA1217 (38% identical).
Diseases named in the same sentence as SRCIN1 in open-access papers:
SRCIN1 is named in the same sentence as 37 diseases in open-access papers, as found by Europe PMC text mining. Sharing a sentence is not in itself a finding about the gene and the disease. The quoted sentences say what the papers report.
breast carcinoma (26 papers, 2008 to 2025). "Aberrant SRCIN1 methylation in cfDNA from plasma could serve as a companion diagnostic biomarker for SRCIN1 inhibitor therapy in the clinical treatment of breast cancer patients." (PMID 38785978, 2024). "Breast cancer cell-derived exosomes were found to deliver miR-20a-5p targeting SRCIN1 to promote osteoclast proliferation and differentiation and to promote breast cancer bone metastasis." (PMID 41430724, 2025). "In the present study, we conducted a genome-wide methylation array analysis to detect hypermethylation at multiple CpG sites in SRCIN1 in breast cancer patients." (PMID 38785978, 2024). "To further understand the impact of SRCIN1 expression on breast cancer, we conducted RNA-seq analysis to explore potential pathways and regulatory proteins linked to SRCIN1." (PMID 38785978, 2024). "Using the Infinium MethylationEPIC BeadChip, we analyzed plasma sample methylation to identify the SRCIN1 gene in breast cancer patients." (PMID 38785978, 2024). "The levels of methylated SRCIN1 in the blood of patients from Taiwan and the USA correlated with the stage of breast cancer." (PMID 38785978, 2024). "For instance, it was reported that MDA-MB-231 breast cancer cell-derived exosomal miR-20a-5p inhibits the expression of SRC kinase signal inhibitor 1 (SRCIN1) and promotes osteoclast formation." (PMID 38448424, 2024). "SRCIN1 hypermethylation was identified in 61.8% of breast cancer tissues from Taiwanese patients, exhibiting specificity to this malignancy." (PMID 38785978, 2024). "Methylation array analysis and quantitative methylation-specific PCR (qMSP) confirmed an increase in the methylation level exceeding 50% at five CpG sites within SRCIN1 in tissue samples from breast cancer patients in both the TCGA and Taiwanese cohorts." (PMID 38785978, 2024). "Among these predicted targets, SRCIN1 possesses tumor-suppressive properties in breast cancer and lung cancer inhibiting cell migration and proliferation." (PMID 39698112, 2024). "To investigate the pathways regulated by SRCIN1 expression in breast cancer, we performed gene silencing in the MCF-7 cell line and utilized RNA-seq analysis combined with MetaCore pathway analyses for data interpretation." (PMID 38785978, 2024). "Analysis of clinical data revealed that increased expression of SRCIN1 was correlated with early-stage and late-stage breast cancer." (PMID 38785978, 2024). "The TCGA RNA-seq data revealed an increase in the expression of SRCIN1 in 72 paired tumor tissue samples compared with normal tissue samples from breast cancer patients (p < 0.001)." (PMID 38785978, 2024). "The percentage of patients with high expression of SRCIN1 was higher in the ER-positive breast cancer (53.4%, p < 0.01) and PR-positive breast cancer (53.6%, p <0.05) groups than in the ER-negative and PR-negative groups." (PMID 38785978, 2024). "To validate the observations of circulating methylated SRCIN1 in breast cancer patients, as identified by a genome-wide methylation array in plasma, we conducted a methylation array analysis on five paired breast cancer tissue samples." (PMID 38785978, 2024). "In breast cancer, lung cancer, and osteosarcoma, SRCIN1 has been demonstrated to function as a tumor suppressor." (PMID 36033827, 2022). "In this review, a synopsis of 15 years of research on the role of p130Cas/BCAR1 and p140Cap/SRCIN1 in breast cancer will be presented." (PMID 34708040, 2021). "(c) The study provides evidence that miR‐20a‐5p transferred from breast cancer cell‐derived exosomes promotes the proliferation and differentiation of osteoclasts by targeting SRCIN1." (PMID 31385464, 2019). "Further, we analysed by FISH a consecutive series of 77 breast cancer patients at diagnosis with a mix of probes for SRCIN1 and the centromeric region (CEP17) of chromosome 17." (PMID 28300085, 2017).
breast carcinoma (continued). "EPIC methylation array analysis revealed SRCIN1 hypermethylation in breast cancer patient plasma, and this marker could distinguish between healthy individuals and patients with varying disease stages, with methylation levels increasing with disease severity." (PMID 38785978, 2024). "The presence of hypermethylated and circulating methylated SRCIN1 specifically in breast cancer samples indicates their utility as promising noninvasive biomarkers for the early detection and prediction of disease progression in breast cancer patients." (PMID 38785978, 2024). "Knockdown of SRCIN1 decreased the viability of breast cancer cells." (PMID 38785978, 2024). "Additionally, we assessed the high-specificity detection of circulating methylated SRCIN1 in the blood of Taiwanese and Western patients with breast cancer." (PMID 38785978, 2024). "SRCIN1 might suppress β-catenin in the breast cancer stem cell niche, thereby promoting antitumor immune defense." (PMID 38785978, 2024). "Finally, further analysis is needed of both BCAR1 and SRCIN1 gene status and regulation in specific breast cancer subtypes, in order to address their real contribution to the biological heterogeneity of human tumors in terms of patient stratification." (PMID 34708040, 2021). "Moreover, in a large cohort of Her2-positive breast cancer patients, high levels of SRCIN1 expression positively correlates with increased survival in patients with high TIAM1 expression." (PMID 33079227, 2021). "Our recent work show that in HER2-related breast cancer, amplification of the ERBB2 locus may lead to SRCIN1 amplification, thus contributing to the biological heterogeneity of this breast cancer subgroup." (PMID 31285546, 2020). "SRCIN1 hypermethylation in the blood may serve as a noninvasive biomarker, facilitating early detection and prognosis evaluation, and SRCIN1-targeted therapies could be used in combination regimens for breast cancer patients." (PMID 38785978, 2024). "To investigate whether high expression levels of SRCIN1 were modulated by DNA hypermethylation of SRCIN1, we treated breast cancer cells with the DNMT inhibitor 5-aza-2′-deoxycytidine (DAC) to suppress the methylation of the SRCIN1 gene and then analyzed the SRCIN1 mRNA expression level." (PMID 38785978, 2024). "Besides the co-amplification with ERBB2 in breast cancer, the SRCIN1 gene might be lost or disrupted in some cases of aggressive neuroblastoma due to the 17q12 chromosomal rearrangement." (PMID 34708040, 2021). "The likelihood that expression and genomic profiling of SRCIN1/p140Cap might impact on the disease was first evaluated in human breast cancer (BC), one of the most common cancers with more than 2 million new cases in 2018 and 450,000 deaths each year worldwide." (PMID 33079227, 2021). "As indicated in the extant literature, miR-20a-5p has been reported to contribute to the development of breast cancer by affecting the regulation of SPRy4-IT1, SRCIN1, and PANDAR gene expression." (PMID 40686703, 2025). "Analysis of our comprehensive dataset, which included three different breast cancer cell lines—MCF7, T47D and MDA-MB231—revealed a significant reduction in cell proliferation upon the silencing of SRCIN1." (PMID 38785978, 2024). "Reduced SRCIN1 expression led to decreased cell viability in the MCF-7, T47D and MDA-MB-231 breast cancer cell lines, as confirmed by more than three technical and biological replicates." (PMID 38785978, 2024). "For our investigation, a human Infinium methylation EPIC array containing plasma samples from Taiwanese breast cancer patients was used to identify a novel hypermethylated gene, SRC kinase signaling inhibitor 1 (SRCIN1/p140cap), specific to breast cancer." (PMID 38785978, 2024). "The adaptor protein p140Cap/SRCIN1 negatively regulates tumor cell features and limits breast cancer progression." (PMID 31285546, 2020).
breast carcinoma (continued). "Numerous researches have revealed that miR-20a-5p is vital for the development and prognosis of breast cancer through the targeted regulation of genes such as SPRy4-IT1, SRCIN1 and PANDAR, and have also provided a breakthrough for drug design and synthesis of breast cancer." (PMID 35577802, 2022). "Previous studies on lung, gastric, cervical, and breast cancers have shown that miR-150-5p promotes cell proliferation and migration by targeting the SRC kinase signaling inhibitor 1 (SRCIN1), a negative regulator of SRC and an experimentally validated direct target of miR-150-5p." (PMID 35565284, 2022). "In 2019, a group of researchers reported that the exosomal miR-20a-5p from breast cancer cells could stimulate osteoclast proliferation and differentiation by targeting SRC kinase signaling inhibitor 1 (SRCIN1), a kinase involved in cell migration." (PMID 35011442, 2021). "In fact, the analysis of 200 ERBB2-amplified tumors showed that the SRCIN1 gene is often (55–60% of ERBB2-amplified breast cancer patients), but not necessarily co-amplified with ERBB2." (PMID 34708040, 2021). "SRCIN1 methylation has not been investigated in any disease, particularly in breast cancer, and its impact on the expression levels under these conditions remains unclear." (PMID 38785978, 2024). "Additionally, to ascertain whether SRCIN1 is a potential drug target, validating its biological function through cell cycle arrest assays and apoptosis analysis is essential, especially in the context of SRCIN1-silenced, untreated and DAC-treated breast cancer cells." (PMID 38785978, 2024). "Interestingly, SRCIN1 hypermethylation did not occur in other cancer types within the Taiwanese and TCGA datasets, confirming the usefulness of SRCIN1 as a biomarker specifically for breast cancer patients." (PMID 38785978, 2024). "Altogether, these results show that the SRCIN1 gene is frequently, but not obligatorily, co-amplified with ERBB2 in breast cancers, arguing for a potential role of SRCIN1 as a determinant of the clinical heterogeneity of ERBB2 tumours." (PMID 28300085, 2017).
lung carcinoma (8 papers, 2014 to 2024). "We discovered that the methylation levels of SRCIN1 in lung cancer, colon cancer, esophageal cancer and uterine cancer samples from Taiwanese patients were not significantly different between tumor and normal tissues." (PMID 38785978, 2024). "Additional studies show that miR-150 promotes the proliferation and migration in lung cancer by targeting SRC kinase signaling inhibitor 1 (SRCIN1) and SRC activity." (PMID 26205403, 2015). "SRC Kinase Signaling Inhibitor 1 (SRCIN1) is identified to be regulator for affecting cell proliferation and migration in lung cancer." (PMID 35912006, 2022). "Consistent with the Taiwanese data, the TCGA dataset also revealed that methylation at the five specific CpG sites of SRCIN1 did not significantly differ among lung cancer, colon cancer, esophageal cancer, uterine cancer, liver cancer, pancreatic cancer and gastric cancer patients." (PMID 38785978, 2024).
colorectal cancer (6 papers, 2018 to 2022). A primary or metastatic malignant neoplasm that affects the colon or rectum. "An in-depth study on how VEGF signaling is promoted by miR-181a in preclinical models of colorectal cancer identified SRC kinase signaling inhibitor 1 (SRCIN1), an angiogenesis suppressor, as a key target of miR-181a." (PMID 35449729, 2022). "Hsa-miR-374a-5p interferes with carcinogenesis by regulating Srcin1, which contributes to the growth and metastasis of colorectal cancer, or by regulating WIF1 that acts as tumor suppressor." (PMID 29293623, 2018). "In colorectal cancer (CRC)–a very aggressive metastatic tumor with active angiogenesis–miR-181a induced tube-formation in ECs and promoted angiogenesis in vivo by directly inhibiting SRC kinase signaling inhibitor 1 (SRCIN1, also known as p140Cap)." (PMID 35626707, 2022).
neuroblastoma (6 papers, 2019 to 2023). Neuroblastoma (NB) is the most common solid, extracranial childhood tumor. "In neuroblastoma patients, SRCIN1 mRNA levels represent an independent risk factor, which is inversely correlated to disease aggressiveness." (PMID 33079227, 2021). "RNAseq profiles of a large cohort of neuroblastoma patients show that SRCIN1 mRNA levels are an independent risk factor inversely correlated to disease aggressiveness." (PMID 31285546, 2020). "In high-risk patients, CGH+SNP microarray analysis of primary neuroblastoma identifies SRCIN1 as frequently altered by hemizygous deletion, copy-neutral loss of heterozygosity, or disruption." (PMID 31285546, 2020). "Although the clinical relevance of SRCIN1 expression in neuroblastoma has been demonstrated, since it is an independent risk factor inversely correlated to disease aggressiveness, the importance of these genetic aberrations should be better investigated in a larger cohort of patients." (PMID 34708040, 2021). "This study provides the first evidence that the SRCIN1/p140Cap adaptor protein is a key player in neuroblastoma as a new independent prognostic marker for patient outcome and treatment." (PMID 31285546, 2020). "Altogether, these data highlight the potential clinical impact of SRCIN1/p140Cap expression in neuroblastoma tumors, in terms of reducing cytotoxic effects of chemotherapy, one of the main issues for pediatric tumor treatment." (PMID 31285546, 2020). "Indeed, we recently provided the first evidence that the SRCIN1/p140Cap adaptor protein is a key player in neuroblastoma as a new independent prognostic marker for patient outcome and treatment." (PMID 31681758, 2019).
colon cancer (4 papers, 2011 to 2024). "Gain and loss of function approaches in breast and colon cancer cells demonstrated that SRCIN1 inhibits EGFR and Erk1/2 signaling, blocking scatter and proliferation of cancer cells." (PMID 21931769, 2011). "However, some studies defined miR-211 as a tumor promoter, by inhibiting the expression of SRC kinase signaling inhibitor 1 (SRCIN1), miR-211 was proved to promote human non-small cell lung cancer, and by targeting tumor suppressive gene CHD 5, miR-211 can promote human colon cancer." (PMID 28924391, 2017).
gastric cancer (4 papers, 2020 to 2024). A primary or metastatic malignant neoplasm involving the stomach. "Overexpressed miR-150 causes A540 lung cancer cells, breast cancer cell lines, and BGC-823 gastric cancer cells to acquire malignancy behavior through suppressing SRCIN1." (PMID 37924077, 2023). "Moreover, SRCIN1 was explored in lung, breast, and gastric cancer cells and its relation with miR-150 has been shown." (PMID 37924077, 2023). "SRCIN1 has been reported to block ERK signaling, and RASAL1 can act as a tumor suppressor gene in gastric cancer through inactivation of the ERK pathway." (PMID 37149929, 2023).
lung adenocarcinoma (4 papers, 2019 to 2020). A carcinoma that arises from the lung and is characterized by the presence of malignant glandular epithelial cells. "It has been established that miR-873 increases lung adenocarcinoma cell proliferation and migration by targeting SRCIN1, and its expression is decreased in glioblastoma multiforme (GBM) tumour tissues and cell lines." (PMID 32192523, 2020). "miR-873 has also been shown to increase lung adenocarcinoma cell proliferation and migration by targeting SRCIN1, and its expression is decreased in glioblastoma multiforme (GBM) tumor tissues and cell lines." (PMID 31024249, 2019). "However, miR-873 has been reported as an oncogene in lung adenocarcinoma by inhibiting its downstream target SRCIN1." (PMID 31289617, 2019).
osteosarcoma (4 papers, 2017 to 2022). A usually aggressive malignant bone-forming mesenchymal neoplasm, predominantly affecting adolescents and young adults. "Moreover, miR-17-5p promoted cell multiplication and EMT in osteosarcoma (OS) through targeting SRCIN1." (PMID 36033827, 2022). "SRCIN1 is identified to be an inhibitor in lung cancer and breast cancer along with osteosarcoma." (PMID 32964035, 2020).
cervical carcinoma (3 papers, 2021 to 2022). A carcinoma arising from either the exocervical squamous epithelium or the endocervical glandular epithelium. "For example, miR-150-5p contributes to the epithelial–mesenchymal transition and cell growth of cervical carcinoma cells by regulating SRCIN1." (PMID 36118276, 2022). "When transducing miR-150-5p mimics, the expression of SRCIN1 increased, the proliferation and EMT of cervical cancer cells were suppressed significantly, and apoptosis was accelerated by SRCIN1." (PMID 34299149, 2021). "Zhu and Han found that SRCIN1 is a target gene of miR-150-5p and overexpression of SRCIN1 suppressed cell proliferation and EMT in cervical cancer cells." (PMID 36033827, 2022).